VWF (von Willebrand factor)
Diseases named in the same sentence as VWF in open-access papers (continued):
Sharing a sentence is not in itself a finding about the gene and the disease.
thrombotic thrombocytopenic purpura (170 papers, 2005 to 2026). "Thrombotic thrombocytopenic purpura mainly arises from a deficiency or inhibition of ADAMTS13—a metalloproteinase responsible for cleaving a significant portion of von Willebrand factor (vWF)." (PMID 40933296, 2025). "This is dramatically manifest in thrombotic thrombocytopenic purpura, a condition of genetic or acquired deficiency for the protease that cleaves the endothelium-derived platelet binder von Willebrand factor." (PMID 40029709, 2025). "A severe deficiency of ADAMTS13, a metalloprotease that cleaves ultra-large von Willebrand factor (vWF) multimers, causes thrombotic thrombocytopenic purpura (TTP) that is a subtype of primary TMA." (PMID 40990987, 2025). "Severe ADAMTS13 deficiency (the VWF cleaving protease) causes accumulation of ultra-large vWF multimers (ULVWF) that can lead to the clinical picture of thrombotic microangiopathy as seen in its most severe form in thrombotic thrombocytopenic purpura (TTP)." (PMID 35551628, 2022). "Thrombotic thrombocytopenic purpura (TTP) is caused by ADAMTS13 deficiency leading to ultra-large vWF multimers." (PMID 36741833, 2022). "Another disease caused by an abnormal vWF:ADAMTS13 ratio is thrombotic thrombocytopenic purpura (TTP)." (PMID 34208470, 2021). "On the contrary, increased concentrations of ultra-large multimers of vWF lead to thrombotic thrombocytopenic purpura (TTP), which develops due to a deficiency of ADAMTS-13." (PMID 33096906, 2020). "The loss of its function leads to the accumulation of the von Willebrand factor and causes thrombotic thrombocytopenic purpura (TTP)." (PMID 32150898, 2020). "Thrombotic thrombocytopenic purpura (TTP) results from deficient von Willebrand factor (vWF) cleaving zinc metalloprotease ADAMTS13." (PMID 29728803, 2018). "Deficient proteolysis of ULvWF (ultra large von Willebrand factor) due to reduced ADAMTS-13 activity results in disseminated platelet-rich thrombi in the microcirculation characteristic of thrombotic thrombocytopenic purpura." (PMID 23537039, 2013). "Many cases of adult thrombotic thrombocytopenic purpura (TTP) are due to deficient activity of the VWF cleaving protease." (PMID 21876803, 2011). "Thrombotic thrombocytopenic purpura (TTP) is caused by the abundance of uncleaved ultralarge von Willebrand factor multimers (ULvWF) due to acquired (autoantibody-mediated) or congenital vWF protease ADAMTS13 deficiency." (PMID 29728803, 2018). "Severe deficiency of ADAMTS13 (<10 iu/dL) is diagnostic of thrombotic thrombocytopenic purpura (TTP) and leads to accumulation of ultra-large vWF multimers, platelet aggregation, and widespread microthrombi, which can be life-threatening." (PMID 39274365, 2024). "Congenital or acquired defects in ADAMTS-13 are associated with enhancement in large VWF multimers, bringing about the formation of platelet-rich plugs and systemic microthrombosis, a condition called thrombotic thrombocytopenic purpura (TTP)." (PMID 38327640, 2024). "Insufficient ADAMTS13 activity can lead to unregulated VWF platelet-capturing and is a risk factor for thrombosis including thrombotic thrombocytopenic purpura (TTP), myocardial infarction, stroke, and venous thromboembolism." (PMID 38643218, 2024). "Thrombotic thrombocytopenic purpura (TTP) results from a severe deficiency of the specific von Willebrand factor (VWF)-cleaving protease named ADAMTS13 (a disintegrin and metalloprotease with thrombospondin type 1 repeats, member 13)." (PMID 35163523, 2022). "The increase in the level of HMWM of VWF due to ADAMTS-13 deficiency causes thrombotic thrombocytopenic purpura (TTP), characterized by microvascular thrombosis and platelet pool depletion." (PMID 36531725, 2022). "Significantly elevated levels of VWF are observed in thrombotic thrombocytopenic purpura (TTP), which results from a profound deficiency of ADAMTS13." (PMID 34575297, 2021).
thrombotic thrombocytopenic purpura (continued). "Severe ADAMTS13 deficiency causes accumulation of ultra-large vWF multimers (ULVWF) leading to the clinical picture of severe thrombotic microangiopathy as seen in thrombotic thrombocytopenic purpura (TTP)." (PMID 32122366, 2020). "Deficiency of ADAMTS13 causes thrombotic thrombocytopenic purpura (TTP), a disease characterized by overt platelet aggregation through large vWF multimers generating microvascular thrombosis." (PMID 31068896, 2019). "In addition, an anti-VWF antibody, caplacizumab, has already demonstrated promising clinical results in the treatment of thrombotic thrombocytopenic purpura and may also prevent microangiopathy in diseases associated with increased eryptosis." (PMID 30026593, 2018). "It is the presence of these “ultra large” VWF multimers, caused by ADAMTS13 deficiency, that initiates the formation VWF-platelet microthrombi, which characterize thrombotic thrombocytopenic purpura (TTP)." (PMID 28209710, 2017). "A reduction or elimination of the protease activity of ADAMTS13 results in the VWF multimers remaining uncleaved in the circulating blood stream, which ultimately leads to intravascular thrombosis and an associated disorder known as Thrombotic Thrombocytopenic Purpura (TTP)." (PMID 19654870, 2009). "In severe or recurrent cases, caplacizumab provides rapid control of acute thrombotic thrombocytopenic purpura by inhibiting platelet-von Willebrand factor interaction, although its use in pregnancy remains limited." (PMID 41852235, 2026). "Current evidence indicates that vitamin B12 deficiency often co-exists with thrombotic thrombocytopenic purpura, a lethal micro-thrombotic disorder caused by severe ADAMTS13 deficiency and abnormal VWF accumulation." (PMID 40625905, 2025). "Thrombotic thrombocytopenic purpura (TTP) is a life-threatening thrombotic disease characterized by a severe deficiency in the activity of a specific von Willebrand factor (VWF)-cleaving protease, a disintegrin-like metalloproteinase with thrombospondin type 1 motif 13 (ADAMTS-13)." (PMID 40821745, 2025). "Thrombotic thrombocytopenic purpura (TTP), also known as Moschcowitz syndrome, is an uncommon hematological disorder caused by deficiency in ADAMTS-13, a von Willebrand factor (VWF) cleaving protein." (PMID 39221447, 2024). "For example, Caplacizumab, a nanobody against von Willebrand factor, has demonstrated rapid and effective outcomes in treating thrombotic thrombocytopenic purpura with fewer adverse reactions, underscoring the potential of nanobodies in immunotherapy." (PMID 39897125, 2024). "ADAMTS13 (a disintegrin and metalloproteinase with a thrombospondin type 1 motif, member 13) is a metalloproteinase that cleaves the polymers of vWF, and diminished activity of ADAMTS13 is the diagnostic hallmark of thrombotic thrombocytopenic purpura." (PMID 39456810, 2024). "It is used for the treatment of acquired thrombotic thrombocytopenic purpura (aTTP) and works by targeting von Willebrand factor (vWF), inhibiting its interaction with platelets, thus preventing the formation of microthrombi." (PMID 39166870, 2024). "Caplacizumab, a nanobody directed against von Willebrand factor to treat thrombotic thrombocytopenic purpura, was the first clinically approved molecule in Europe and the USA." (PMID 37734558, 2023). "Congenital Thrombotic Thrombocytopenic Purpura is a severe autosomal recessive disorder characterized by uncleaved ultra-large vWF and thrombotic microangiopathy, frequently triggered by infections." (PMID 35746657, 2022). "Lack of ADAMTS-13 can result in persistent von Willebrand factor (vWF), leading to severe thrombotic thrombocytopenic purpura." (PMID 35883515, 2022). "Caplacizumab, an anti-von Willebrand factor (vWF) nanobody, developed for the treatment of thrombotic thrombocytopenic purpura (TTP) is the most developed nanobody, having completed phase III clinical trials." (PMID 33670740, 2021).
thrombotic thrombocytopenic purpura (continued). "The anti-VWF nanobody caplacizumab exerts almost complete inhibition of VWF59 which benefits patients with thrombotic thrombocytopenic purpura." (PMID 32636459, 2020). "For example, caplacizumab (ALX-0081) is the first single domain anti-von Willebrand factor antibody which is going to be marketed for treatment of thrombotic thrombocytopenic purpura and thrombosis by Ablynx Company." (PMID 31531059, 2019). "Yet, most studies about ADAMTS13 have focused on its relationship with VWF or role in thrombotic thrombocytopenic purpura, and limited data are available to corroborate other pathways." (PMID 29615758, 2018). "Force-regulated cleavage of A2 domain of von Willebrand factor (vWF) by ADAMTS13 is a key event in preventing thrombotic thrombocytopenic purpura (TTP)." (PMID 29636514, 2018). "Thrombotic thrombocytopenic purpura (TTP) is a life-threatening disorder characterized by systemic platelet-von Willebrand factor aggregation, organ ischemia and profound thrombocytopenia." (PMID 26022055, 2015). "Thrombotic Thrombocytopenic Purpura (TTP) is an acute, life-threatening thrombotic microangiopathy caused by deficient activity of the von Willebrand factor (VWF) cleaving protease ADAMTS13 (a disintegrin and metalloprotease with thrombospondin type 1 motif, 13th member)." (PMID 25431165, 2014). "CR-TM shares certain clinical similarities with thrombotic thrombocytopenic purpura such as neurological and renal impairment; also both are characterized by circulating platelet aggregates containing ultra large multimers of Von Willebrand factor (VWF)." (PMID 16262899, 2005). "An imbalance in the VWF/ADAMTS-13 axis has been implicated in the pathogenesis of thrombotic disorders, including thrombotic thrombocytopenic purpura (TTP), and may also be relevant in the context of PCS." (PMID 39941459, 2025). "Thrombotic thrombocytopenic purpura is characterized by ADAMTS-13 deficiency, resulting in a deficient excision of the ultra-large VWF multimers presented in the VWF molecule on ECs, causing platelet adhesion and aggregation with rapid generation of disseminated microthrombi." (PMID 38034541, 2023). "Nowadays, one of the nanobodies that has received the European Medicines Agency (EMA) and the USA Food and Drug Administration (FDA) approval is Caplacizumab which has been designed for treatment of thrombotic thrombocytopenic purpura by targeting the von Willebrand Factor (vWF)." (PMID 35656179, 2022). "The correlation between vWF and platelets and the vWF/platelet ratio might also suggest that targeting this axis with caplacizimab is now used in the treatment of thrombotic thrombocytopenic purpura (TTP) may be of benefit." (PMID 34476137, 2021). "Disordered regulation of von Willebrand factor (VWF) is a key feature in the pathogenesis of thrombotic thrombocytopenic purpura, and may be involved in other types of thrombotic microangiopathies." (PMID 33391257, 2020). "Promising agents under evaluation for micro-thrombosis secondary to thrombotic thrombocytopenic purpura include, caplacizumab (an inhibitor of the glycoprotein-Ib/IX-Von-Willebrand factor axis), N-acetyl cysteine, recombinant ADAMTS13, and anti-plasmocyte compounds." (PMID 31741612, 2019). "When cleavage is inhibited, resulting in increased vWF, thrombotic thrombocytopenic purpura may occur." (PMID 29023508, 2017). "However, since its discovery in 2001, most ADAMTS13 research has focused on its interactions with VWF and its role in thrombotic thrombocytopenic purpura." (PMID 27787621, 2017). "Adamts13 encodes a large circulating protease responsible for processing multimeric von Willebrand factor (vWF) in vivo; mutations in human ADAMTS13 cause thrombotic thrombocytopenic purpura and variations in ADAMTS13 activity are associated with other thrombotic abnormalities." (PMID 25835743, 2015).
thrombotic thrombocytopenic purpura (continued). "TAMOF is characterized as a thrombotic microangiopathic process, similar to that described in thrombotic thrombocytopenic purpura (TTP), which is characterized by decreased ADAMTS13 protease activity causing accumulation of large, multimeric von Willebrand Factor (vWF)." (PMID 24408224, 2014). "Deficiency of plasma ADAMTS13 activity could result in an accumulation of newly released ultra large (UL) VWF on endothelial cells where it is synthesized and in blood, leading to a potentially fatal syndrome, thrombotic thrombocytopenic purpura (TTP)." (PMID 24790789, 2013). "Abnormal persistence of ultra-large VWF (ULVWF) multimers is caused by severe ADAMTS13 deficiency, which triggers thrombotic thrombocytopenic purpura (TTP), thereby predisposing microvascular thrombosis." (PMID 40362344, 2025). "Its clinical use in acquired thrombotic thrombocytopenic purpura (TTP) demonstrates the therapeutic potential of directly targeting the vWF-ADAMTS13 axis in thrombotic disorders." (PMID 41007843, 2025). "Thrombotic thrombocytopenic purpura (TTP) is a microangiopathic hemolytic anemia associated with ADAMTS-13 deficiency, a cleaving protease of von Willebrand factor (vWF)." (PMID 39978057, 2025). "Thrombotic Thrombocytopenic Purpura (TTP) is an extremely rare microangiopathic hemolytic anemia characterized by a deficiency of ADAMTS-13, a von Willebrand Factor (vWF) cleaving protease." (PMID 39978057, 2025). "Thrombotic thrombocytopenic purpura (TTP) is a thrombotic process characterized by multiorgan failure secondary to microvascular thrombi comprising platelets and von Willebrand factor." (PMID 39445270, 2024). "Caplacizumab, a nanobody that blocks VWF is currently being used for the treatments of adults with acquired thrombotic thrombocytopenic purpura (TTP) in preventing the development of potentially life threatening microvascular thrombosis." (PMID 38545417, 2024). "Thrombotic thrombocytopenic purpura (TTP) is a rare and life-threatening thrombotic microangiopathy (TMA) related to a severe ADAMTS13 deficiency, the specific von Willebrand factor (VWF)-cleaving protease." (PMID 37176509, 2023). "There is a marked difference in the levels of VWF and VWF-propeptide in healthy individuals after desmopressin/endotoxin when compared to patients with diabetes, thrombotic thrombocytopenic purpura (TTP), or sepsis." (PMID 33542410, 2021). "Thrombotic thrombocytopenic purpura, hereditary or acquired, is secondary to deficiency of ADAMTS13 (a disintegrin and metalloproteinase with a thrombospondin type 1 motif, member 13), which causes the formation of large von Willebrand factor (vWF) multimers and platelet aggregation." (PMID 34208103, 2021). "Complete deficiency in ADAMTS‐13 is the cause of thrombotic thrombocytopenic purpura (TTP), a thrombotic microangiopathy (TMA) whose hallmark symptoms are platelet‐ and VWF‐rich microvascular thrombi." (PMID 31294335, 2019). "In thrombotic thrombocytopenic purpura (TTP) patients, an acquired or inherited deficiency of the VWF cleaving protease ADAMTS13 results in accumulation of ultralarge (UL)-VWF multimers." (PMID 30759116, 2019). "Thrombotic thrombocytopenic purpura (TTP) is an autoimmune disease caused by a deficiency of ADAMTS13, a von Willebrand Factor (vWF)-cleaving metalloprotease." (PMID 31831041, 2019). "The presence of increased levels of UL-VWF multimers in plasma has been shown to initiate the formation of VWF-platelet microthrombi, resulting in debilitating thrombotic complications such as thrombotic thrombocytopenic purpura (TTP)." (PMID 29326937, 2017). "Thrombotic thrombocytopenic purpura (TTP) is a rare human disease characterized by thrombocytopenia, accumulation of VWF-rich thrombi in the microvasculature, anemia and organ dysfunction." (PMID 25297919, 2015).
thrombotic thrombocytopenic purpura (continued). "A delayed clearance of vWF, as is seen in conditions such as thrombotic thrombocytopenic purpura (TTP) and hemolytic uremic syndrome (HUS), is unlikely the cause of high vWF antigen in HIV." (PMID 25814984, 2015). "The zinc metalloprotease ADAMTS13 is a multidomain protein that cleaves von Willebrand Factor (VWF) and is implicated in Thrombotic Thrombocytopenic Purpura (TTP) pathogenesis." (PMID 19654870, 2009). "Thrombotic thrombocytopenic purpura (TTP) is a life-threatening syndrome caused by a congenital or acquired reduction in the activity of the enzyme ADAMTS-13, which is involved in the cleavage of von Willebrand factor." (PMID 39941509, 2025). "Thrombotic thrombocytopenic purpura (TTP) is a rare and life-threatening blood disease caused by severe deficiency of a disintegrin and metalloprotease with thrombospondin type I repeats-13 (ADAMTS-13) enzyme, a von Willebrand factor (VWF)-cleaving protease." (PMID 40034892, 2025). "Thrombotic thrombocytopenic purpura (TTP) is a thrombotic microangiopathy characterized by reduced activity of ADAMTS13, a protease responsible for cleaving von Willebrand factor (VWF)." (PMID 38957258, 2024). "Since larger VWF multimers possess higher platelet aggregation capacity, insufficient cleavage of UL-VWF multimers due to a deficiency in ADAMTS13 activity results in lethal thrombosis in patients with thrombotic thrombocytopenic purpura (TTP)." (PMID 39247211, 2024). "The interplay between vWF and ADAMTS13 are crucial in the pathogenesis of thrombotic microangiopathy such as thrombotic thrombocytopenic purpura (TTP)." (PMID 38069327, 2023). "In a non-cancer setting, the dysfunctional ADAMTS-13 in patients with thrombotic thrombocytopenic purpura (TTP), results in the presence of highly adhesive ultra-large VWF multimers in the blood that bind tightly to platelets to form aggregates." (PMID 33571850, 2021). "Caplacizumab (ALX-0081) was recently approved by the FDA to treat thrombotic thrombocytopenic purpura (TTP), a disease characterized by the presence of active ultra-large VWF multimers due to insufficient ADAMTS13 activity." (PMID 33883551, 2021). "Thus, in patients with low ADAMTS13 activity, platelets become more easily activated by the ultralarge VWF multimers, which can lead to a condition of thrombotic thrombocytopenic purpura (TTP)." (PMID 33490118, 2020). "This small experiment is in agreement with a previous study which showed comparable IC90 values for the anti-VWF aptamer ARC1779 in VWF dependent platelet function tests in healthy volunteers and thrombotic thrombocytopenic purpura patients." (PMID 32636459, 2020). "ADAMTS13, a metalloprotease that is able to cleave von Willebrand factor (VWF), was first discovered in thrombotic thrombocytopenic purpura (TTP)." (PMID 32075652, 2020). "Thrombotic thrombocytopenic purpura (TTP) is a rare blood disorder caused by the absence of the specific proteolytic activity of ADAMTS-13 toward the von Willebrand factor, which causes clots in small vessels throughout the whole body." (PMID 32150898, 2020). "Thrombotic thrombocytopenic purpura (TTP) is a microangiopathic thrombotic process which can result in multi-organ failure characterised by widespread microvascular thrombi consisting of platelets and von Willebrand Factor (VWF)." (PMID 30559606, 2018). "VWF is produced and released by vascular endothelial cells, and is frequently used as an indicator of endothelial cell activation in vascular disorders such as thrombotic thrombocytopenic purpura (TTP) and sepsis." (PMID 22125593, 2011). "Indeed, children with cerebral malaria (CM) had VWF propeptide levels exceeding those typically observed in fulminant vascular diseases such as thrombotic thrombocytopenic purpura (TTP)." (PMID 19300493, 2009).